HLA-B (major histocompatibility complex, class I, B)
Diseases named in the same sentence as HLA-B in open-access papers (continued):
Sharing a sentence is not in itself a finding about the gene and the disease.
gout (continued). "Several single-nucleotide polymorphisms (SNPs) in the coding regions of genes associated with the drug response in gout treatment have been identified, including CYP2C9, HLA-B, and G6PD." (PMID 40870966, 2025). "The obtained results showed that the frequency of HLA-B*58:01 in gout patients was 6.02%, with 12.03% of individuals being heterozygous (*X/*58:01) and no individuals being homozygous (*58:01/*58:01)." (PMID 40870966, 2025). "This study investigated the genotype frequency of HLA-B*58:01 and its association with paraclinical characteristics and PSORS1C1 rs9263726 in gout patients from Northeast Vietnam." (PMID 40870966, 2025). "White blood cell counts differed significantly between the *X/HLA-B*58:01 and *X/*X groups in male gout patients." (PMID 40870966, 2025). "White blood cell counts were significantly higher in male gout patients with the *X/HLA-B*58:01 genotype compared to those with the *X/*X genotype (p = 0.018)." (PMID 40870966, 2025). "The distribution of rs9263726 and the correlation with HLA-B*58:01 in gout patients were similar to that seen in the healthy Han population." (PMID 30080910, 2018). "The genotypes of rs9263726 and HLA-B*58:01 in 205 Han patients with gout were investigated to detect their relationship in gout patients." (PMID 30080910, 2018). "Therefore, the HLA-B*58:01 allele has been approved as a diagnostic marker for ALP-induced SCARs, and its screening is recommended before using ALP for gout treatment." (PMID 34573954, 2021). "HLA-B*58:01 genotyping could guide the indication for allopurinol in Kinh Vietnamese patients with gout." (PMID 32746911, 2020). "The addition of HLA-B polymorphic variants into the model did not affect gout risk in men and hyperlipidemic patients." (PMID 30934611, 2019). "Also, in Han patients with gout, the LD between rs9263726 and HLA-B*58:01 was similar to that seen in the healthy Han population." (PMID 30080910, 2018). "This is the first study to identify the allele and genotype frequencies of HLA-B*58:01 using the Sanger sequencing method and to investigate its association with paraclinical characteristics and the SNP rs9263726 of the PSORS1C1 gene in randomly selected gout patients living in Northeast Vietnam." (PMID 40870966, 2025). "Furthermore, previous studies have shown a strong relationship between the presence of HLA-B*58:01 and severe symptoms such as SJS and TEN in patients with ALP-induced SCARs; however, the relationship between HLA-B*58:01 and mild symptoms in patients with gout treated with ALP is unclear." (PMID 34573954, 2021). "Notably, although HLA-B*58:01 may be a cause for the occurrence of MCARs in patients with gout, this correlation was not as strong as that previously reported in patients with SCAR." (PMID 34573954, 2021). "Conduct a cost-utility analysis of sequential ULT treatment strategies for gout, including strategies with and without HLA-B*58:01 genotyping, before treatment initiation, with a view to determining optimal gout management." (PMID 37842401, 2023). "Our analysis suggests that performing HLA-B*5801 testing prior to allopurinol administration reduces the number of SJS/TEN cases and may prevent death attributable to SJS/TEN in patients with gout." (PMID 24732692, 2014). "It is well known that the presence of HLA-B*58:01 is closely related to the occurrence of severe adverse drug reactions (SJS, SJS/TEN, TEN, and DRESS) in the skin of patients (SCARs) when ALP is used for gout treatment, especially for Black and Asian people rather than white people." (PMID 34573954, 2021). "HLA-B*58:01 was not consistently associated with the SNP rs9263726 of the PSORS1C1 gene, suggesting that rs9263726 may not be a reliable surrogate marker for HLA-B*58:01 in gout patients." (PMID 40870966, 2025).
leprosy (17 papers, 2014 to 2026). Leprosy is a chronic infectious disease affecting primarily the skin and peripheral nervous system. "We also observed a leprosy association in the class I region, at HLA-B*49:01 (p × 6.02 × 10−4, FDR = 0.0156), which is independent of HLA-DQB1*04:02." (PMID 36121873, 2022). "The univariable borderline association of HLA-DRB1*07:01 with leprosy was fully explained by HLA-C*07:06/HLA-B*44:03 by multivariable analysis." (PMID 32776973, 2020). "Based on the result of the SBT, we can see a spectrum of HLA-B allele frequency in the leprosy patients from Papua." (PMID 33064728, 2020). "The leprosy protective signal #2 is dominated by alleles that are part of a HLA-C*07:06 ~ HLA-B*44:03 ~ HLA-DRB1*07:01 haplotype." (PMID 32776973, 2020). "HLA-B*49 was found to be significantly associated with protection against leprosy per se in a Turkish population." (PMID 25605482, 2015). "Among them, only one leprosy patient carried one risk allele of HLA-B*13:01 and in that case, DDS was removed from MDT." (PMID 25165865, 2014). "In previous studies, only HLA-B*13:01 was strongly associated with DHS in leprosy Han Chinese (odds ratio 122.1, p-value = 6.038 × 10−12 and odds ratio 20.53, p-value = 6.84 × 10−25) and dapsone-induced DRESS in non-leprosy Thais (odds ratio = 60.75, p-value = 0.0001)." (PMID 34017337, 2021). "Furthermore, an association was demonstrated between the HLA-B*13:01 allele and the development of hypersensitivity reactions (SCARs) in Asian patients with leprosy treated with oral dapsone." (PMID 34577605, 2021). "However, a study conducted in 872 Asian patients with leprosy treated with dapsone found that the presence of the HLA-B*13:01 allele was useful as a risk predictor for dapsone hypersensitivity syndrome (with a sensitivity of 85.5% and specificity of 85.7%)." (PMID 34577605, 2021). "We identified four amino acids in HLA-DRβ1 (phenylalanine and aspartic acid in positions 13 and 57), HLA-B (glutamic acid in position 63), and HLA-A (lysine in position 19) that fully explained the associations of class I and class II alleles with leprosy in our sample." (PMID 32776973, 2020). "Functional studies analyzing the impact of HLA-DRβ1 57D and 13F, HLA-B 63E and HLA-A 19K in the context of the specific protein structure of the associated HLA alleles will provide additional insight in the role of HLA molecules in leprosy susceptibility." (PMID 32776973, 2020). "In addition, haplotypes containing HLA-DRB3~ HLA-DRB1*12:02 and HLA-C*07:06~ HLA-B*44:03~ HLA-DRB1*07:01 alleles were found as two independent protective factors for leprosy." (PMID 32776973, 2020). "In addition, we show that four amino acid polymorphisms in HLA-DRβ1, HLA-B and HLA-A are sufficient to explain the majority of leprosy-HLA associations which opens the way for select protein-HLA peptide binding studies." (PMID 32776973, 2020). "HLA-B*49 and HLA-C*05 were also associated with protection against B leprosy." (PMID 25605482, 2015). "In addition, detection of the HLA-B 13:01 risk allele in patients with leprosy using single specific primer-polymerase chain reaction may help physicians to distinguish DHS from lepra reactions that share similar clinical symptoms." (PMID 28167593, 2017). "HLA-B*13:01 allele has been identified as the genetic determinant of dapsone hypersensitivity syndrome (DHS) among leprosy and non-leprosy patients in several studies." (PMID 34017337, 2021). "Meanwhile, HLA-B*13:01 allele sensitively and specifically predicted DHS in Han Chinese leprosy patients (85.5 and 85.7%, respectively)." (PMID 34017337, 2021). "HLA-B*13:01 is validated as a biomarker for DHS in leprosy patients in Papua, Indonesia, and can potentially be a good predictor of DHS to help prevent this condition in the future." (PMID 33064728, 2020). "An increased frequency of HLA-B*07 was observed in B leprosy patients (18.81% vs. 12.78%; p = 0.043, OR = 1.58, 95% CI = 1.02–2.5, pc = 1.37)." (PMID 25605482, 2015).
leprosy (continued). "Up to now, the HLA-B*13:01 test was performed in 33 new leprosy patients and six new dermatitis herpetiformis patients in our clinics before treatment using MDT or DDS alone." (PMID 25165865, 2014). "Nevertheless, there are no data describing whether HLA class I, II alleles and cytochrome P450 is a valid marker for prediction of dapsone-induced SCARs in non-leprosy patients in addition to HLA-B*13:01." (PMID 34017337, 2021). "Furthermore, DHS in Han Chinese leprosy patients were found to carry HLA-B*13:01 (OR 122.1, p-value = 6.038 × 10−12 and OR 20.53, p-value = 6.84 × 10−25), Indonesian leprosy patients (OR 233.46, p-value = 7.11 × 10−9), and Korean patients (OR 73.67)." (PMID 34017337, 2021). "For example, HLA-B*13:01 is associated with dapsone-induced hypersensitivity reactions among leprosy patients and non-leprosy patients in Chinese and Thai." (PMID 33995375, 2021). "HLA-B*13:01 is validated as a biomarker for DHS in leprosy patients in Indonesia." (PMID 33064728, 2020). "HLA-B*53 (6.43% vs. 2.93%; p = 0.050, OR = 2.28, 95% CI = 1.05–4.94, pc =1.60) and HLA-C*16 (10.4% vs. 5.44%; p = 0.030, OR = 2.02, 95% CI = 1.10–3.67, pc = 0.48) were also more frequent in B leprosy patients than in healthy controls." (PMID 25605482, 2015). "HLA-C*12 was previously shown to be associated with susceptibility to leprosy per se in a population in Southeast Brazil; however, no study has shown an association between HLA-B*58 and leprosy." (PMID 25605482, 2015). "Furthermore, HLA-B*13:01 testing is recommended for new patients with leprosy being initiated on dapsone therapy in China; an ongoing clinical trial is examining the efficacy of CYP2C9*3 and HLA-B alleles screening to prevention of phenytoin-induced SCAR in China population." (PMID 35548363, 2022). "Dapsone, an antimicrobial agent used in the treatment of leprosy or Pneumocystis jirovecii pneumonia, can induce a hypersensitivity syndrome similar to DRESS syndrome, and it was significantly associated with the HLA‐B*13:01 allele in Chinese, Thai, and Koreans." (PMID 35070271, 2022). "Screening for HLA-B*13:01 may potentially reduce DHS incidence significantly and benefit many aspects of the leprosy control program in Indonesia." (PMID 33064728, 2020). "Thus, HLA-B*13:01 is strongly associated with dapsone-induced SCARs including of SJS-TEN and DRESS in leprosy and non-leprosy Asian patients." (PMID 34017337, 2021). "When we directly compared LCs between a single leprosy biopsy and a single normal skin biopsy from which we performed bead-based LC enrichment (STAR Methods), we detected elevated expression of IDO1, STAT1, HCAR3, and MHC class I molecules (HLA-A, HLA-B, and HLA-F) in LCs in leprosy infection." (PMID 33053333, 2020).
type 1 diabetes (17 papers, 2007 to 2025). "In this study, we characterised circulating autoreactive CD8+ T cells in children with type 1 diabetes with HLA-B*3906+ and HLA-A*2402+ genotypes which are associated with increased risk and early onset of disease." (PMID 31660582, 2020). "It is beyond the scope of the current study to consider fine-mapping of the MHC region, and it is well established that the HLA-DQB1, HLA-DRB1, HLA-A and HLA-B genes are the primary determinants of the MHC risk in type 1 diabetes." (PMID 28983737, 2018). "HLA-B*39:06 was the class I allele most widely associated with type 1 diabetes risk, whereas HLA-B*57:01 decreases the risk." (PMID 28550517, 2017). "However, the KIR–HLA-I interaction analysis uncovered 22 interactions, with nine HLA-I (three HLA-A and six HLA-B allele products) and 14 KIRs affecting progression to type 1 diabetes." (PMID 40835749, 2025). "Collectively, these studies prompt questions in relation to the presentation of β cell autoantigens to CD8+ T cells by HLA‐B*39‐ and HLA‐A*24‐encoded HLA class I molecules and the potential of these events to drive β cell destruction and accelerate type 1 diabetes progression." (PMID 31660582, 2020). "We provide evidence that autoreactive CD8+ T cells restricted by HLA‐B*3906 and HLA‐A*2402‐encoded HLA class I molecules display an antigen‐experienced phenotype and acquire enhanced effector function during the period leading to clinical diagnosis of type 1 diabetes." (PMID 31660582, 2020). "HLA‐B*3906 is also known to associate with a relatively younger age of diagnosis and notably, this allele has been reported to be more frequent in children who progress to clinical type 1 diabetes under the age of 5·5 years 20, an age group which corresponds with the cohort examined in this study." (PMID 31660582, 2020). "In HLA-B*3906+ children with newly diagnosed type 1 diabetes, we observed an increase in PPI5–12‐specific transitional memory CD8+ T cells compared to non‐diabetic, age‐ and HLA‐matched subjects." (PMID 31660582, 2020). "This is the first study to report autoreactive CD8+ T cells restricted by HLA‐B*3906 in blood samples from individuals with type 1 diabetes." (PMID 31660582, 2020). "In type I diabetes mellitus, HLA-A, HLA-B, HLA-C, HLA-DPB1 and GAD1 exhibited significantly different expression levels." (PMID 26062681, 2015). "Highly associated pathways such as KEGG "Type I Diabetes," "Antigen processing and presentation," and "Systemic lupus erythematosus" share several genes, particularly HLA class I and II paralogs (HLA-DRB1, HLA-DQB1, HLA-DQA1, HLA-B)." (PMID 39495786, 2024). "Here we show that the transitional memory subset of B*3906‐restricted PPI‐specific transitional memory CD8+ T cells comprises a higher proportion of the total PPI‐specific population in HLA‐B*3906+ children with new‐onset type 1 diabetes compared to HLA‐matched control subjects." (PMID 31660582, 2020). "Additionally, we had the opportunity to assess PPI5–12‐specific CD8+ T cells 5 years prior to the diagnosis of type 1 diabetes in an HLA‐B*3906+ child who was aged 3·3 years at the time of blood draw." (PMID 31660582, 2020). "As HLA‐B*39 carries the strongest type 1 diabetes risk of all HLA class I gene polymorphisms, we sought to determine whether HLA‐B*39‐restricted CD8+ T cells with specificity for β cell antigens could be detected in individuals with type 1 diabetes." (PMID 31660582, 2020). "In cluster 2, the significantly enriched genes were HLA-B, HLA-A, HLA-DRB1, HLA-DQA1 and HLA-DQB1, with all genes related to allograft rejection, GVHD, type I diabetes, autoimmune thyroid disease and viral myocarditis." (PMID 37063831, 2023). "Whereas in our pathway analysis, more genes are identified as part of Type I diabetes mellitus and Allograft rejection pathways (i.e. CD28, HLA-B, HLA-C, HLA-DMB, HLA-DPA1, HLA-DQA2, HLA-DRA, IL12A)." (PMID 22046267, 2011).
type 1 diabetes (continued). "This was also reflected in the KEGG pathway analysis of trans-mQTLs where type 1 diabetes was found to be an enriched pathway of relevance in human pancreatic islets, including the following genes: PTPRN2, HLA-DRB1, HLA-B, HLA-C, HSPD1 and HLA-DRB5 (Padj = 6.0×10−4)." (PMID 25375650, 2014). "We also found that compared to type 1 diabetes subjects with classical HLA haplotypes, non-classical HLA subjects had a significantly higher frequency of HLA-B*39:06:02 (p-value=0.01) and HLA-C*07:02:01 (p-value=0.03) alleles, known to be involved in activating the immune response." (PMID 39185409, 2024).
Arthritis (16 papers, 2009 to 2025). Inflammation of a joint. "The association between HLA-B*27 and arthritis is one of the strongest known relationships between an HLA loci and a disease." (PMID 33910121, 2021). "In particular, HLA-B*27:03, an arthritis-associated HLA-B*27 subtype, had a reduced ability to form cell-surface homodimers." (PMID 33092023, 2020). "Then the genotype HLA-B27:04/B*40:01 can improve diagnostic accuracy, and patients with HLA-B*27:04/B*46:01 had a high risk of arthritis and enthesitis." (PMID 33490092, 2020). "For example, B*08, B*27, and B*38 can induce PsA development, whereas HLA-B*27:05:02 is associated with arthritis, enthesites, dactylites, and symmetric sacroiliitis, and HLA-B*08:01:01 and HLA-C*07:01:01 are associated with erosive arthritis, dactylites, and asymmetric sacroiliitis." (PMID 37238999, 2023). "In addition, human leukocyte antigen (HLA) typing detected the HLA-B*40 allele, which is reported to increase the risk of arthritis, suggesting the genetic vulnerability of NAT002 to hyperostosis, which was observed around her chest clavicle." (PMID 34410389, 2021). "In addition, the arthritis-associated HLA-B*2705 allele was shown to form more cell-surface homodimers than the non-associated HLA-B*2709 allele." (PMID 33092023, 2020). "HLA-B*18 demonstrated similar distribution: 23.2% in inflammatory low back pain, 25.6% in sacroiliitis, 25.2% in arthritis, and 24.4% in enthesitis." (PMID 40806743, 2025). "We observed that arthritis develops much closer to the appearance of PsO in the HLA-B*27:05:02 or B*39:01:01 subset than in the HLA-C*06:02 subset of PsA cases." (PMID 25948071, 2015). "We found the most frequent occurring haplotype was significantly increased in patients with BD that were positive for HLA-B*51 and in patients with BD and arthritis." (PMID 20011079, 2009). "HLA-B*35 was present in 29.2% of patients with inflammatory low back pain, 21.6% with reduced lumbar mobility, 23.3% with radiographic sacroiliitis, 28.9% with arthritis, 24.4% with enthesitis, and 34.6% with elevated CRP/ESR levels." (PMID 40806743, 2025). "The data showed that HLA-B*27:05:02 and HLA-B*39:01:01 were susceptibility alleles for PsA, but are not high-risk alleles for PsO in the absence of arthritis, and HLA-B*08:01 was associated with PsA susceptibility but appears protective for PsO, being significantly reduced in frequency in PsO." (PMID 25948071, 2015). "Our review showed that the presence of HLA-B*27 was higher in the Pso patients who developed arthritis than in the Pso patients who did not." (PMID 34127053, 2021). "Notably, the presence of HLA-B*27 was higher in PsO patients who developed arthritis than those who did not, suggesting a possible differentiation capability for HLA-B*27 in identifying PsO patients with or without PsA." (PMID 38994340, 2024). "In addition, the homozygous TT genotype showed a higher risk for neurologic involvement (OR = 2.55) and epididymitis (OR = 3.18) than arthritis in the HLA-B*51 carriers, although the risks were not significant." (PMID 30514861, 2018).